SETD6 (SET domain containing 6, protein lysine methyltransferase)
Diseases named in the same sentence as SETD6 in open-access papers (continued):
Sharing a sentence is not in itself a finding about the gene and the disease.
osteosarcoma (2 papers, 2017 to 2025). A usually aggressive malignant bone-forming mesenchymal neoplasm, predominantly affecting adolescents and young adults. "It is also conceivable that SETD6-mediated inhibition of IκBα seen in our model is lost in the osteosarcoma cancer cell line." (PMID 28122346, 2017). "However, SETD6 had been shown previously to be involved in transcriptional repression of p65 in the osteosarcoma cell line U-2 OS cells." (PMID 28122346, 2017).
cervical cancer (1 paper, 2025). A primary or metastatic malignant neoplasm involving the cervix. "Notably, SETD6 methylation of PLK1 slows cervical cancer progression through mitosis and thereby restrains proliferation." (PMID 40102573, 2025).
COVID-19 (1 paper, 2025). A disease caused by infection with severe acute respiratory syndrome coronavirus 2. "Besides the NF-κB activity, SETD6 expression level is downregulated in peripheral blood mononuclear cells from patients with severe COVID-19 and from deceased patients." (PMID 40102573, 2025).
diabetic nephropathy (1 paper, 2023). "In diabetic nephropathy, downregulation of SETD6 protects podocytes from apoptosis and mitochondrial dysfunction induced by high glucose and palmitic acid by activating the Nrf2-Keap1 signaling pathway." (PMID 36707848, 2023).
diffuse gastric adenocarcinoma (1 paper, 2023). An adenocarcinoma arising from the stomach. "This is in accordance with previous findings in other cancer types, showing that overexpression of SETD6 was present in diffuse gastric adenocarcinoma, adenocarcinoma of the colon, rectum, cecum, and rectal mucinous adenocarcinoma compared to their respective normal tissues." (PMID 36604642, 2023).
head and neck carcinoma (1 paper, 2011). A carcinoma that arises from the head and neck region.
lung carcinoma (1 paper, 2023). "Four other genes involved in the ceRNA network, including MCM7, NCAPG2, SETD6, and KIF22 have also been reported to involved in lung cancer progression." (PMID 37098483, 2023).
prostate tumor (1 paper, 2026). "SETD6 KO GO Group 2 contains genes promoting prostate tumor growth and migration via regulation of ubiquitin transferases, including DCUN1D5, UBE2S, and CDC20." (PMID 41540805, 2026).
cancer (10 papers, 2011 to 2026). A tumor composed of atypical neoplastic, often pleomorphic cells that invade other tissues. "Furthermore, SETD6 function has been associated with several cancer types." (PMID 37690684, 2023). "In many of these cases, SETD6 methylation was demonstrated to have pronounced effects on the cellular activities of the target proteins showing that SETD6 regulates different cellular processes in normal cells and various types of cancer." (PMID 41540805, 2026). "The SETD6 (SET domain-containing protein 6) protein lysine methyltransferase regulates various cellular processes including cancer initiation and progression." (PMID 41540805, 2026). "By contrast, and outside of a cancer model, SETD6 silencing has been shown to protect mouse podocytes from glucose- and palmitic-acid-induced apoptosis." (PMID 40102573, 2025). "The PKMT SETD6 has a fundamental role in the regulation of several biological processes and pathologies including cancer." (PMID 40809945, 2025). "Given that the delivery of recombinant SETD6 protein has therapeutic potential to dampen an overactive immune response, it would be interesting to apply this delivery system to cancer or disease models in which SETD6 antagonizes disease progression." (PMID 40102573, 2025). "Nonetheless, SETD6 is positioned as a key regulator of cancer cell proliferation and therefore regulates the cell cycle." (PMID 40102573, 2025). "SETD6 expression is dysregulated in numerous cancers, and this correlates with poor patient survival rates for several types of tumor." (PMID 40102573, 2025). "Little is known about the regulation of SETD6 expression, but differences in SETD6 expression between different tissues and cancers indicate that its expression is meaningful and tightly orchestrated." (PMID 40102573, 2025). "Previous studies showed SETD6 is overexpressed in multipe human cancers and participates in tumorigenesis." (PMID 36604642, 2023). "Previous studies in multiple cancer types have attempted to elucidate the potential mechanisms of SETD6-mediated cancer development." (PMID 36604642, 2023). "SET domain containing 6 (SETD6) has been shown to be upregulated in multiple human cancers and can promote malignant cell survival." (PMID 36604642, 2023). "Overexpression of SETD6 in transformed urothelial cells increased cell survival and colony formation while knockdown in cancer cells decreased both parameters." (PMID 28122346, 2017). "However, the role of SETD6 as a promotor or suppressor of cancerous phenotypes is contextual regarding cancer type." (PMID 40102573, 2025). "Throughout this Review, the role of SETD6 in the regulation of substrate protein function, transcriptional regulation and other biological processes has been discussed in the context of various cancer models." (PMID 40102573, 2025). "Moreover, Nrf2/Keap1 signaling, which is a key signaling pathway that can enhance anti-oxidative stress capacity of cancer cells and exert anti-apoptotic effects, was also regulated by SETD6 in our study." (PMID 36604642, 2023). "In this regard, further screening and identification of selective inhibitors of SETD6 may exert anti-cancer effects in LUAD." (PMID 36604642, 2023). "Although the exact reason for this different response is unclear at this time, we speculate that the contextual difference in the role of NF-κB in transformed vs. cancer cells may determine the methylation ability of SETD6." (PMID 28122346, 2017). "Whether SETD6 promotes or suppresses cancerous properties depends on the type of cancer." (PMID 40102573, 2025). "Furthermore, SETD6 expression is dysregulated in several types of cancer." (PMID 40102573, 2025). "Furthermore, SETD6 regulates numerous cancerous phenotypes and guards cancer cells from apoptosis." (PMID 40102573, 2025).
cancer (continued). "We verified the four up-regulated lncRNAs (TCONS_00020615, TCONS_00055555, TCONS_00106091, and TCONS_00130858) and eight cancer-related mRNAs (CDCA3, DIAPH3, MCM7, NCAPG2, TPD52, PRC1, SETD6, and KIF22) involved in the ceRNA network by qRT-PCR." (PMID 37098483, 2023). "The SETD6 PKMT is known as lysine mono-methyltransferase that methylates a wide spectrum of substrate proteins with important roles in normal cell physiology and in cancer development." (PMID 41540805, 2026). "This SETD6-mediated methylation of E2F1 may have implications for the progression of diseases, including cancer." (PMID 37690684, 2023).
tumor (5 papers, 2015 to 2026). "Importantly, higher SETD6 expression was significantly associated with poorer overall survival and higher rates of regional lymph node metastasis in our study, indicating that SETD6 correlated with aggressive tumor behavior in LUAD patients." (PMID 36604642, 2023). "The expression of endogenous SETD6 mRNA and protein has been observed in a wide variety of cell lines that can be used as models for studying the role of SETD6 in these tumor types." (PMID 40102573, 2025). "We found that SETD6 showed significantly higher protein levels in tumor samples compared with adjacent normal tissues both by western blotting or IHC analysis." (PMID 36604642, 2023). "The expression of SETD6, a gene that may also impair anti-tumour immune response by dysregulation of the NF-kB pathway, was also reduced in FA PMBCs but remain roughly the same in BM." (PMID 26466379, 2015). "SETD6, which is highly expressed in LUAD tumor tissues, plays an important role in promoting the malignant behaviors of LUAD via likely the NF-κB and Nrf2 signaling pathways." (PMID 36604642, 2023). "Compared with non-tumorous tissues, SETD6 was overexpressed in tumor tissues, and its overexpression significantly correlates with higher rates of regional lymph node metastasis and poor prognosis in patients with LUAD." (PMID 36604642, 2023). "We found that SETD6 expression was not significantly correlated with gender, smoking index, clinical stage and tumor size." (PMID 36604642, 2023). "Taking together, these data indicated that SETD6 may participate in the process of apoptosis and oxidative stress of LUAD cells through NF-κB and Keap1/Nrf2 pathway, thus affecting the development of tumor." (PMID 36604642, 2023).
SETD6 also shares sentences with these, for which no sentence is quoted: acute monocytic leukemia (1 paper); adenocarcinoma (1); colorectal cancer (1); familial colorectal cancer type X (1); gastric cancer (1); liver disease (1); neurological diseases (1); rectal mucinous adenocarcinoma (1).